EPHA2 (EPH receptor A2)
Diseases named in the same sentence as EPHA2 in open-access papers (continued):
Sharing a sentence is not in itself a finding about the gene and the disease.
glioblastoma (continued). "On evaluating her tumor sample before enrollment, the immunohistochemistry (IHC) study demonstrated an EphA2-positive glioblastoma." (PMID 34235085, 2021). "To this end, we engineered CAR T cells targeting Ephrin type-A receptor 2 (EphA2) that is abundantly overexpressed in glioblastoma." (PMID 33046212, 2020). "We have recently shown the anticancer proprieties of GLPG1790, a new pan inhibitor of the Eph receptors with a strong efficiency versus EphA2, versus several breast, rhabdomyosarcoma, and glioblastoma cell lines, both in vitro and in vivo." (PMID 32184826, 2020). "These EphA2-specific T cells were demonstrated to identify and kill glioblastoma cells expressing EphA2." (PMID 32811512, 2020). "It was shown that EphA2 protein levels are significantly decreased following ephrin A1–PE38QQR administration in glioblastoma cells." (PMID 32811512, 2020). "A bispecific anti-EphA2/EphA3 antibody triggers internalization of EphA2 and EphA3 leading to reduced tumorigenicity of glioblastoma." (PMID 32629797, 2020). "Combined expression of EphA2, EphA3, EphB2, and IL-13RA2 is observed in almost 100% of patients with glioblastoma patients." (PMID 30366424, 2018). "The molecular action of EphA2 in glioblastoma involves decreased Erk phosphorylation, Akt interaction, Sox downregulation, and altered invasiveness of stem cells." (PMID 29682554, 2018). "As opposed to healthy tissues, EphA2 has been found highly expressed in specimens of glioblastoma, and increased expression of EphA2 has been shown to correlate with poor survival rates." (PMID 29849945, 2018). "Here, we analyzed the expression of Eph receptor A3, one of the most up-regulated factors in glioblastoma cells cultured under tumorsphere-forming conditions, together with EphA2 and EphB2 receptors." (PMID 27494882, 2016). "We compared these results to the U251 glioblastoma cell line, which expresses high levels of EphA2 but low amounts of TF, and confocal microscopy analysis showed a strong membranous EphA2 staining but a weak TF signal." (PMID 27246245, 2016). "Overexpression of TF in U251 glioblastoma cells lead to co-localization with EphA2 at the leading edge and FVIIa-dependent cleavage of EphA2." (PMID 27246245, 2016). "We took advantage of the fact that ephrinA5 (eA5) is a ligand that binds EphA3, EphA2 and EphB2 receptors, and used it to construct a novel targeted anti-glioblastoma cytotoxin." (PMID 27494882, 2016). "The results revealed that EphA2 might serve as a potential therapeutic target for inhibiting HCMV infection in glioblastoma cells." (PMID 40661971, 2025). "Notably, EphA2-CAR-T cells were developed and tested on glioblastoma, where these cells recognized and suppressed EphA2-positive glioblastoma cells with significant reduction in in vivo tumor growth." (PMID 39596256, 2024). "EphA2 drives resistance to the VEGF-a-targeting monoclonal antibody bevacizumab, as a study conducted in glioblastoma patients revealed that patients who developed resistance to bevacizumab had high expression of EphA2, as well as proangiogenic factors such as FGF2, and AGPT2." (PMID 39596256, 2024). "The experiment was replicable with EphA2-CART in a glioblastoma model." (PMID 37754534, 2023). "In contrast, in glioblastoma, EphA2 signaling decreases AKT function by reduced phosphorylation." (PMID 36835335, 2023). "The new dasatinib-derived EphA2 inhibitor, compound 4a, was demonstrated to have improved specificity while retaining significant inhibitory actions toward EphA2 and proliferation in glioblastoma cells." (PMID 36830852, 2023). "To explore whether Eph receptors implicate in HCMV infection of glioblastoma, we used siRNA screening to target the members of the Eph receptor family and found that EphA2 played a crucial role in HCMV infection." (PMID 37146061, 2023). "Altogether, EphA2 is crucial for HCMV infection of glioblastoma cells." (PMID 37146061, 2023).
glioblastoma (continued). "Importantly, the HCMV infection was inhibited by the treatment of inhibitor or antibody targeting EphA2 in glioblastoma cells." (PMID 37146061, 2023). "We further explored the role of EphA2 in HCMV infection in glioblastoma cells." (PMID 37146061, 2023). "In fact, EphA2 is overexpressed in many solid tumors, like gastric, esophageal, colorectal, cervical, breast, ovary, prostate, pancreas, neck, renal, lung, bladder cancers, melanoma, and glioblastoma." (PMID 36142306, 2022). "Moreover, CAR-T cells targeting 3 glioblastoma associated antigens (HER2, IL13Rα2, and EphA2) were also developed and showed even more effectiveness as compared to the bispecific CAR-T." (PMID 35603195, 2022). "Thus, targeting EPHA2 not only reduced glioblastoma stemness but also suppressed PDGF-AA-induced tumor growth." (PMID 35105853, 2022). "In addition, EphA2 can promote self-renewal and tumorigenicity of tumour-propagating cells in glioblastoma as these were suppressed upon siRNA-mediated knockdown of EphA2 expression." (PMID 33430066, 2021). "In glioblastoma, overexpression of EphA2 was shown to correlate with poor prognosis." (PMID 33430066, 2021). "Human CD19+ EphA2-specific CAR T cells efficiently killed glioblastoma cells." (PMID 33046212, 2020). "The novel EphA2 inhibitor candidate 4a based on dasatinib was shown to feature an ameliorated selectivity profile while maintaining potent inhibitory effects against EphA2 as well as cytotoxic properties in glioblastoma cells." (PMID 32811512, 2020). "Of 14 glioblastoma specimens, 13 possessed elevated EPHA2 levels." (PMID 34766125, 2020). "The previous study, exploring the mechanism underlying Eph receptor induce cancer recurrence demonstrated that co-expression of EphA2 and EphA3 led to the high clonogenicity and tumorigenic potential in recurrence of glioblastoma which has been shown in both in vitro and in vivo models." (PMID 32093644, 2020). "Finally, several other antigens on glioblastoma are targeted in other trials, e.g., ephrin type-A receptor 2 (EphA2) (NCT02575261), GD2 (NCT03252171), and mucin 1 (MUC1) (NCT02839954, NCT02617134)." (PMID 31779130, 2019). "In the previous reports, one family member, EphA2, is strongly overexpressed in many types of tumor, such as glioblastomas, ovarian cancers and prostate adenocarcinomas, and the increased expression of EphA2 correlates with enhanced metastatic potential and poor prognosis." (PMID 24606764, 2014). "High levels of EphA2 have been reported in diverse cell lines and clinical specimens, including breast, colon, prostate, non-small cell lung cancers, aggressive melanomas and glioblastoma." (PMID 21264258, 2011). "Recently, a novel TanCAR targeting interleukin-13 receptor subunit alpha-2 (IL-13Rα2) and ephrin type-A receptor 2 (EphA2) was shown to be effective in both in vitro and in vivo glioblastoma (GBM) models." (PMID 36853475, 2023). "Furthermore, HCMV infection was also impaired in optimal glioblastoma organoids by EphA2 inhibitor." (PMID 37146061, 2023). "Furthermore, EphA2 has been found to drive tumorigenicity in glioblastoma." (PMID 37146061, 2023). "Moreover, inhibition of Akt-EphA2 cross-talk suppressed glioblastoma stem cell properties." (PMID 35654777, 2022). "Transfection with full-length human ephrin A1 into glioblastoma multiforme (GBM) cells exhibits a dramatic suppression of EphA2 and inhibits multiple malignant features, including impaired anchorage-independent growth, proliferation, and migration." (PMID 32811512, 2020). "pp65 and survivin are also being targeted together with EphA2 through a multi-peptide vaccine (ETAPA I) in HLA-A*0201 positive patients with a newly diagnosed, unmethylated, and untreated glioblastoma (NCT05283109)." (PMID 41208963, 2025).
glioblastoma (continued). "utilized the tissues from the glioblastoma margin to establish glioblastoma organoids (GBOs), and then cocultured the GBOs with HCMV after treatment with a 2,5-dimethylpyrrolizidine benzoic acid derivative, an EphA2 antagonist." (PMID 40661971, 2025). "For example, in glioblastoma, invasiveness of tumor cells is supported by ligand-independent, AKT-mediated phosphorylation of EphA2 S897, an event inhibited by ephrinA1 stimulation both in vitro and in vivo." (PMID 39596256, 2024). "Here we found that EphA2, a member of receptor tyrosine kinases (RTKs) family, played a crucial role in HCMV infection of glioblastoma cells." (PMID 37146061, 2023). "More interestingly, Gopal showed a novel crosstalk mechanism involving the eHsp90α-LRP1 dependent regulation of EphA2 function, in which the eHsp90α-LRP1 signalling axis regulates AKT signalling and EphA2 activation during glioblastoma cell invasion." (PMID 35883467, 2022). "Isaacs’ group showed a novel crosstalk mechanism involving eHsp90-LRP1 dependent regulation of EphA2 function, in which the eHsp90-LRP1 signalling axis regulates AKT signalling and EphA2 activation during glioblastoma cell invasion." (PMID 35835845, 2022). "In glioblastoma, cell invasion and motility were the result of eHsp90 promoting recruitment of LRP1 to EphA2 in an Akt-dependent manner also dependent on EphA2-S897 phosphorylation." (PMID 36060252, 2022). "The role of EphA2 in GBM (GlioBlastoma Multiforme) has been widely investigated." (PMID 36142306, 2022). "In vivo testing of three antigen-targeted CAR T cells against glioblastomas (HER2, IL13Ra2, EphA2) led to successful antitumor responses against almost 100% of the tumour cells from patient-derived glioblastoma cell lines." (PMID 35205725, 2022). "In glioblastoma (GBM), stimulation of the cells with EGF induced MEK- and RSK-dependent EphA2 S897 phosphorylation." (PMID 33572284, 2021). "Furthermore, it has been shown that EphA2 and EphA3 receptors are highly expressed in glioblastoma multiforme (GBM), where they control angiogenesis and sustain GBM stem cells by renewal of tumor-propagating cells that show stem-like features." (PMID 35056098, 2021). "Accordingly, antibody (against glioblastoma stem cells surface markers glycoprotein cluster of differentiation 44 (CD44) and ephrin receptor A2 (EPHA2)-antisense oligodeoxynucleotides (ASOs) strategy against FAM107A) were established for the treatment of GBM." (PMID 33804473, 2021). "Moreover, very little is known about Eph receptor signaling in glioblastoma (GBM) despite that EphA2 overexpression drives cell proliferation via MEK/ERK in GBM and cell invasion via AKT signaling in glioma stem cells." (PMID 32352518, 2020). "It is important to note that glioblastomas overexpressing Eph A2 are characterized by high activation of AKT which, in turn, phosphorylates EphA2 on S897, and converts EphA2 from a tumor suppressor to a pro-invasive oncogenic protein." (PMID 30279357, 2018). "In some cell types, such as glioblastoma multiforme cells, EFNA1 expression downregulates EPHA2 and suppresses EPHA2-mediated oncogenesis." (PMID 20979646, 2010). "This circuit is primed by heterogeneous glioblastoma neo-antigens (like EGFRvIII) and subsequently eliminates target cells using tandem CARs that recognize homogenous but nonspecific antigens in glioblastoma (like EphA2 and IL13Rα2)." (PMID 40308611, 2025). "CAR-T cell therapy for glioblastoma (GBM) targets several antigens, including interleukin-13 receptor α2 (IL13Rα2), human epidermal growth factor receptor 2 (HER2), epidermal growth factor variant III (EGFRvIII), and erythropoietin-producing hepatocellular carcinoma A2 (EphA2)." (PMID 40092990, 2025). "For example, in a glioblastoma model, bispecific CAR T-cells targeting both interleukin-13 receptor subunit alpha-2 (IL-13Rα2) and ephrin type-A receptor 2 (EphA2) demonstrated enhanced efficacy and reduced antigen escape compared to single CAR bearing T-cells." (PMID 39317919, 2024).
glioblastoma (continued). "A trial of personalized CAR T cells against one of the common glioblastoma targets, including EGFRvIII, IL13Ra2, HER2, EphA2, CD133, and GD2, has published initial results for a cohort of three patients who received EphA2-CART administered in a single dose intravenously." (PMID 37754534, 2023). "While many tumor cells, including glioblastoma, express a type of Eph receptor known as EphA2, most human tissues, including the brain, do not; therefore, EphA2 is an attractive site for immunotherapy." (PMID 37568717, 2023). "Treatment with anti-EphA2 antibody significantly decreased HCMV infection of glioblastoma cells in a dose-dependent manner and showed no cytotoxicity." (PMID 37146061, 2023). "EphA2 is overexpressed in glioblastoma cells and glioblastoma cancer-initiating cells, without a detectable presence in normal tissues." (PMID 36721153, 2023). "These tracers target membrane proteins whose expression is altered in glioblastoma (including the EGFR, DLL4, EPHA2, CD47, AC133 antigen, and MT1-MMP): several components of the tumor microenvironment including vessels, macrophages, and extracellular matrix proteins." (PMID 35008238, 2021). "CAR T cells targeting EphA2 showed a dose-dependent cell killing of esophageal squamous cell carcinoma (ESCC) cells and have been optimized for the adoptive T cell therapy of EphA2+ glioblastoma for further clinical development." (PMID 33101285, 2020). "Regarding vasculogenic mimicry, CDH5 regulates EPH Receptor A2 (EphA2) expression in melanoma cells and, conversely, CDH5 expression was significantly decreased after knockdown of hypoxia-inducible factors (HIF1α or HIF2α) in glioblastoma." (PMID 31324051, 2019). "Curcumin dose-dependently downregulates the expression of EphA2, PI3K, and MMP2 to block the EphA2/PI3K/MMP-2 signaling pathway, thereby suppressing ECM remodeling as well as glioblastoma cell migration and invasion, ultimately disrupting VM formation in glioblastoma." (PMID 41019994, 2025). "The glioblastoma antigens currently targeted in the clinic, often in combination, are Cluster of Differentiation proteins (CD133, CD44 & CD70), IL receptors (IL-13Ra2), EGFR and EGFRvIII, ephrin receptor A2 (EphA2), human epidermal growth factor receptor 2 (HER2) and B7-H3." (PMID 41208963, 2025). "Conversely, EphA2 and EphA10 displayed a down-regulation in kidney chromophobe (KICH) and glioblastoma multiforme (GBM)." (PMID 38952552, 2024). "In conclusion, we have identified EphA2 as an important host factor mediating entry and fusion of HCMV with glioblastoma cells, which may assist future studies striving for a better understanding of how HCMV infects glioblastoma cells and for potential new targets of innovative antiviral strategies." (PMID 37146061, 2023). "When EphA2-specific CAR T cells were embedded in a tumouroid with glioblastoma cells, surrounding CAR T cells swarmed towards the tumouroid, whereas no recruitment was observed when CAR T cells were co-embedded with EphA2-negative fibroblasts in the tumouroid." (PMID 33046212, 2020).
melanoma (77 papers, 2004 to 2026). A malignant, usually aggressive tumor composed of atypical, neoplastic melanocytes. "EphA2 has been shown to be a prognostic marker in a number of solid organ cancers including breast, colorectal and melanoma, and has been associated with adverse pathological features in PCa." (PMID 35869144, 2022). "wtEphB6 restrained the oncogenic signaling of EphA2 and induced anoikis, while mutEphB6 (a missense Q926R mutation, found in lung cancers and melanomas), promoted cell adhesion-mediated drug resistance (CM-DR) to paclitaxel." (PMID 33572284, 2021). "EphA2 has previously been detected in vertical growth phase cutaneous melanoma samples and strong EphA2 staining was associated with increased melanoma thickness and increased proliferation (Ki67)." (PMID 25594008, 2014). "Mutations in EPHA3 have been detected in melanoma, and several ephrin-derived peptide antigens (from EPHA2, EPHA3 and EPHB6) can be recognized by cancer-specific cytotoxic T-cells." (PMID 21494657, 2011). "Our transcriptomic analysis showed that loss of SIRT2 in both P/VG and metastatic melanoma cell lines was associated with decreased expression of EGFR and EPHA2, receptors that are important for the development, proliferation and acquisition of multidrug resistance by melanoma cells." (PMID 31091806, 2019). "It remains to be elucidated whether high expression of CD13/ANPEP is associated with propensity of melanoma cells to exhibit ligand-independent EPHA2 signaling." (PMID 29048432, 2017). "Targeting CD13/ANPEP by a blocking antibody induced apoptosis in both parental A375- and BRAFi-resistant daughter cells as well as in melanoma cells with intrinsic BRAFi resistance and led to dephosphorylation of EPHA2 on S897, previously demonstrated to cause inhibition of the migratory capacity." (PMID 29048432, 2017). "The ability of mEphA2 vaccines to impact EphA2-negative tumors such as the B16 melanoma may suggest that such beneficial immunity may be directed against alternative EphA2+ target cells, such as the tumor-associated vascular endothelial cells." (PMID 15563374, 2004). "These melanoma-private mutations occurred in genes linked to chromatin regulation (ARID1A and ARID2), cell growth (e.g., PIK3CA), cell adhesion (e.g., EPHA2), splicing (SF3B1), angiogenesis (PTPRB), and classic tumor suppressors (NOTCH3, CDKN2A, and PTEN)." (PMID 41516405, 2026). "As well as curcumin, imatinib, and thalidomide have all been shown to inhibit melanoma VM, concomitant with decreases in EPHA2, VE-cadherin, PI3K, VEGF, HIF-1, MMP-2, and MMP-9 expression and/or activity." (PMID 40507830, 2025). "We repeated these experiments in the malignant melanoma A375 cell line, where EphA2 is endogenously expressed." (PMID 38915729, 2024). "WRC is activated by EphA2 through RAC1; therefore, WRC is an important intersection in melanoma migration from oncogenic BRAF signaling and Pten loss-mediated signaling." (PMID 38233537, 2024). "For example, in melanoma, the invasion depth of tumor lesions correlated with increased expression of genes like EphA2, promoting evasion from the immune system and preventing recruitment of T lymphocytes." (PMID 39596256, 2024). "EphA2 is a mediator of resistance to vemurafenib and it has been shown that suppressing EphA2 reduces Akt/erk phosphorylation and inhibits melanoma progression in mice." (PMID 36830852, 2023). "Other commonly evaluated markers were some of those that have previously been reported as VM-associated in melanoma, including MMP-2, MMP-9, and EphA2." (PMID 36823554, 2023). "Curcumin has the ability to inhibit the growth of implanted melanoma VM channels by regulating angiogenesis factors related to EphA2/PI3K/MMPs signaling pathway." (PMID 35248069, 2022). "Studies aimed at testing the role of these proteins in promoting VM in melanoma have shown that the down-regulation of VE-cadherin or EphA2 inhibits VM." (PMID 34476217, 2021).